MTOR (mechanistic target of rapamycin kinase)
Diseases named in the same sentence as MTOR in open-access papers (continued):
Sharing a sentence is not in itself a finding about the gene and the disease.
pancreatic cancer (536 papers, 2009 to 2026). "Drug sensitivity analysis for high and low risk subtypes showed that pancreatic cancer had a lower IC50 value for PI3K/Akt/mTOR signal transduction pathway inhibitors Buparlisib, Rapamycinm, AZD8055, AZD2014, and AZD6482." (PMID 41253932, 2025). "Bioinformatics studies and protein chip analyses identified an association between overexpressed MXRA5 and PI3K-Akt-mTOR cascade in pancreatic cancer cells." (PMID 39149564, 2024). "In summary, we characterize the translational targets of rapamycin in 4EBP1 deficient pancreatic cancer cells and show that mTOR translationally controls the p70-S6K protein expression." (PMID 36900235, 2023). "The significance of the ATF4/TXNIP/REDD1/mTOR pathway was further supported by associated expressions in xenograft tumors as well as human pancreatic cancer samples." (PMID 38089448, 2022). "This study investigated the processes underlying the development of GEM resistance in pancreatic cancer cells and the effect of the mTOR inhibitor Evr therein." (PMID 33849427, 2021). "Administering BITC to mice caused decreased phosphorylation of PI3K/Akt/FOXO1/PDK1/mTOR/FOXO3a, which suppressed pancreatic cancer cell growth and induced apoptosis." (PMID 34025409, 2021). "GDSC analysis showed that mTOR inhibitors are very sensitive to pancreatic cancer cells with mutations in EWSR1.FLI1 and RNF43." (PMID 34461940, 2021). "Triptolide induced apoptosis in pancreatic cancer cells, causing the inactivation of Akt/mTOR/p70S6K and upregulation of the ERK1/2 pathway." (PMID 34025409, 2021). "The association of PKD1-induced mTOR pathway can be used as a therapeutic strategy for the development of new drugs to target pancreatic cancer." (PMID 31819177, 2020). "Mammalian target of rapamycin (mTOR) is known to be associated with cancer progression as well as CSC maintenance in pancreatic cancer." (PMID 32575925, 2020). "Significantly enriched pathways for up-regulated genes were found to include ECM organization and receptor interaction, focal adhesion-PI3K-Akt-mTOR signaling pathway, and integrin signaling pathway, which have well-known associations with pancreatic cancer." (PMID 33194391, 2020). "In another study, overexpression of miR-21 caused resistance to gemcitabine of SUIT-2 and Panc-1 pancreatic cancer cells due to increased activity of PI3K/AKT/mTOR signaling as a consequence of the high suppression of PTEN by miR-21." (PMID 32182839, 2020). "The mTOR is often deregulated in the pancreatic cancer and its activation is associated with poor prognosis." (PMID 29915574, 2018). "We have previously shown that TRAIL can cause the dephosphorylation of the mTOR substrate 4E-BP1 in pancreatic cancer cells." (PMID 29233971, 2017). "In these altered signaling pathways, we focused on the study of AMPK, Akt and mTOR as representatives, which have been recognized as associated with malignant behaviors of pancreatic cancer." (PMID 29018223, 2017). "Activation of the mammalian target of rapamycin (mTOR) pathway is associated with various pancreatic neoplasms." (PMID 26683340, 2015). "The activation of this pathway and expression of the downstream effector molecule S6 ribosomal protein can enhance chemosensitivity and promote apoptosis in pancreatic cancer cells However, TQ pretreatment significantly attenuates the phosphorylation of mTOR, S6, and upstream Akt caused by GEM." (PMID 36686732, 2022). "Next, we found that gemcitabine combined with an mTOR inhibitor (RAD001) could reverse the decrease in chemosensitivity caused by LAT2 overexpression in pancreatic cancer cells." (PMID 30419950, 2018). "Interestingly, annexin-A2 also has been implicated in gemcitabine resistance in pancreatic cancer via the AKT/mTOR pathway." (PMID 29443941, 2018).
pancreatic cancer (continued). "Multiple pathways associated with aggressive biological behaviors in pancreatic cancer were enriched, including FoxO signaling pathway, mTOR signaling pathway, PI3K-Akt signaling pathway, AMPK signaling pathway, MAPK signaling pathway, Ras signaling pathway, HIF-1a signaling pathway and others." (PMID 29018223, 2017). "Similarly, use of everolimus in a patient with Peutz–Jeghers syndrome-induced advanced pancreatic cancer with presumed mTOR hyperactivation through loss of STK11/LKB1 leads to 9 months progression-free survival." (PMID 27200288, 2016). "Although the overall level of activity of mTOR inhibitors in pancreatic cancer was modest, the finding that the activity could be linked to a biomarker was critical to support the conduction of the clinical study." (PMID 20664591, 2010). "Moreover, KEGG pathway enrichment indicated anti-pancreatic cancer effects closely linked to the PI3K-Akt/mTOR signaling axis, one of the most frequently activated pathways in cancers, promoting cell survival, proliferation, and resistance to anticancer therapies." (PMID 41006588, 2025). "However, pancreatic cancer cells bypass mTOR inhibition through loss of 4EBP1 expression, suggesting that S6 may have a differential role in mRNA translation." (PMID 36900235, 2023). "Gemcitabine has been the standard treatment for advanced-stage pancreatic cancer since it inhibits cell proliferation and causes apoptosis of tumor cells through the activation of the adenosine monophosphate-activated protein kinase/mammalian target of rapamycin (AMPK/mTOR) pathway." (PMID 35800364, 2022). "It has been previously reported that EIF3 complex instability is linked to deregulation of MTOR, leading to increased translation of oncogenic proteins and malignant transformation in pancreatic cancer, further establishing this interaction in pancreatic cancer." (PMID 36517508, 2022). "Additionally, the regulatory effect of theAkt/mTOR pathway might be associated with Bcl-2/caspase-9/c-myc-mediated apoptosis, resulting in cell proliferation in pancreatic cancer cells." (PMID 30429828, 2018). "This is consistent with a previous study, in pancreatic cancer, where Sesn2 can increase glycolysis and promote the proliferation of pancreatic cancer cells, and both of these pro-tumorigenic effects were reversed by mTOR inhibitors." (PMID 41614860, 2025). "Here, we report the CuB-induced mitophagy of pancreatic cancer via the PI3K/Akt/mTOR and PINK1/Parkin pathways, subsequently modulating the key enzyme levels in the glycolysis pathway and reducing the energy supply for pancreatic cancer cells." (PMID 40944197, 2025). "SLC5A1 has been confirmed to be highly expressed in many malignant tumors by several studies, including our research, and a study on pancreatic cancer demonstrated that SLC5A1 regulates cancer cell growth through AMPK/mTOR signaling." (PMID 40963858, 2025).
pancreatic cancer (continued). "In pancreatic cancer, m6A stimulates the PI3K/Akt/mTOR pathway, driving cancer cell proliferation, whereas m1A and m5C are linked with activation of the mTOR pathway and unfavorable prognoses." (PMID 40406121, 2025). "Diminished expression of m1A and its regulatory enzyme ALKBH1 in pancreatic cancer correlates with a dire prognosis, expediting disease progression via the mTOR and Erythroblastic Leukemia Viral Oncogene Homologs (ErbB) signaling pathways." (PMID 39791162, 2025). "We previously examined the antitumor effects of short interfering RNA nanoparticles targeting mammalian target of rapamycin (mTOR) in an orthotopic pancreatic cancer mouse model." (PMID 39794664, 2025). "Advanced glycation end‐products and activation of the AKT/mTOR pathway in type 2 diabetes can also promote pancreatic cancer development." (PMID 40129249, 2025). "DDIT4-AS1b signifies a grim prognosis in pancreatic cancer, influencing stem cell traits and response to chemotherapy via activation of the mTOR signaling pathway." (PMID 39791162, 2025). "A study indicated that the dual downstream blockade of the MAPK and PI3K/AKT/mTOR pathways was more effective in a therapeutic strategy for pancreatic cancer." (PMID 40142329, 2025). "In pancreatic cancer, mTOR affects cell proliferation and metastatic ability by regulating the phosphorylation of YBX1, further promoting the occurrence of EMT." (PMID 40573188, 2025). "It is well known that the PI3K/Akt/mTOR pathway contributes to Gemcitabine resistance in pancreatic cancer, and the dysregulation of this pathway is frequently observed in pancreatic cancer." (PMID 41471783, 2025). "For instance, in pancreatic cancer, the inhibition of the mTOR signaling pathway can effectively promote the phenotypic transformation of cancer stem cells, thereby inhibiting their metastatic ability." (PMID 40573188, 2025). "We interrogated a study examining drug-tolerant persistence following mTOR inhibition in pancreatic cancer." (PMID 40998801, 2025). "Subsequently, it was further investigated the role of ROS in mediating apoptosis and inhibiting pro-survival signaling pathways, including Akt, NF-κB, and mTOR, by bardoxolone methyl in pancreatic cancer cells." (PMID 40732256, 2025). "Combined with cisplatin, it can affect the PI3K/AKT/mTOR signal transduction pathway, which leads to markedly increased cell apoptosis, indicating that rapamycin can mediate the sensitivity of pancreatic cancer cells to cisplatin." (PMID 40362181, 2025). "Since the AKT/mTOR pathway is a key mechanism for gemcitabine resistance in pancreatic cancer cells, this study demonstrated that harmine and gemcitabine, in combination, significantly suppressed the AKT/mTOR signaling pathway." (PMID 39954215, 2025). "Previous studies have shown that silencing PROK1 exerts its anti-pancreatic cancer effects by inhibiting the PI3K/AKT/mTOR pathway, leading to increased levels of Bax and Cleaved Caspase 3, and decreased levels of PCNA and Bcl-2 in pancreatic cancer cells." (PMID 40961099, 2025). "We herein report the inhibitory effects of the mTOR inhibitor rapamycin on tumor growth in a novel established mouse model of pancreatic cancer using human pancreatic cancer cell line-derived organoids." (PMID 39794664, 2025). "In osteosarcoma, Prkci promoted cell growth via the Akt/mTOR pathway, while in pancreatic cancer, Prkci and RIPK2 jointly enhanced NF-κB/JNK/ERK signaling, driving cancer cell proliferation and invasion." (PMID 40840329, 2025). "Omipalisib (PI3K/Akt/mTOR inhibitor) together with Trametinib has shown good results in Pancreatic cancer cells recently." (PMID 38474109, 2024). "Inhibiting mTOR has been shown to suppress the growth of CD133+ pancreatic cancer stem cells and their sphere-forming ability, thereby confirming its role in self-renewal and CSC maintenance." (PMID 39201332, 2024).
pancreatic cancer (continued). "Our study revealed that TET inhibited the phosphorylation of AKT and mTOR in pancreatic cancer cells in a dose- and time-dependent manner." (PMID 38987818, 2024). "Studies have reported that the use of PI3K inhibitors can induce a decrease in c-Myc expression in pancreatic cancer cells, while the use of c-Myc inhibitors can attenuate PI3K/AKT/mTOR-induced pancreatic cancer cell proliferation." (PMID 38914714, 2024). "Metformin has been shown to improve the prognosis of pancreatic cancer by inhibiting the mTOR pathway, leading to decreased energy consumption and cell growth and increasing insulin sensitivity, causing decreased blood glucose levels." (PMID 38611003, 2024). "Collectively, these findings further confirm that RCE inhibits the AKT/mTOR pathway in human pancreatic cancer cells to induce autophagy." (PMID 39139643, 2024). "In pancreatic cancer, the target of hispidulin is the vascular endothelial growth factor (VEGF) receptor 2 mediated PI3K/Akt/mTOR signalling pathway in endothelial cells, thereby suppressing pancreatic tumor cell growth and angiogenesis." (PMID 39713250, 2024). "GSK343, an EZH2 inhibitor, demonstrates anti-tumor effects by inducing autophagy and downregulating AKT/mTOR signaling in pancreatic cancer cells." (PMID 39403146, 2024). "In recent years, TSN has shown anticancer effects and can suppress the proliferation, migration, and invasion of pancreatic cancer cells, and it suppressed pancreatic cancer progression via down regulating Akt/mTOR signaling." (PMID 39707196, 2024). "They decrease pancreatic cancer cell growth by suppressing glycolysis via the PI3K/AKT/mTOR pathway and decreasing glucose uptake and lactate production by decreasing mRNA levels of genes for GLUT-1 and lactate dehydrogenase A." (PMID 38611003, 2024). "It had been demonstrated that MST2 upregulation facilitated apoptosis in pancreatic cancer cells by activating PI3K/AKT/mTOR pathway." (PMID 39640582, 2024). "This suggests that the PI3K/AKT/mTOR pathway is an upstream signaling pathway regulating c-Myc expression in pancreatic cancer cells." (PMID 38914714, 2024). "Its high expression has been correlated with CD147 expression, proliferation, angiogenesis, and mammalian target of rapamycin (mTOR) signaling in pancreatic cancer cells." (PMID 38534987, 2024). "In patients with pancreatic cancer, high TGM2 expression was positively associated with a poor prognosis.Kaempferol induces ROS-dependent apoptosis by downregulating TGM2 and the Akt/mTOR signaling pathway in PANC-1 and Mia PaCa-2 pancreatic cancer cells." (PMID 38324023, 2024). "Another microRNA, miRNA-99b-5p, regulates through the mTOR/AR signaling pathway to trigger autophagy, and inhibit the proliferation of pancreatic cancer cells." (PMID 39056768, 2024). "A dual inhibitor of PI3K/mTOR named Dactolisib showed antitumor activity in Pancreatic cancer cells and xenografts, and in combination with gemcitabine showed even better results." (PMID 38474109, 2024). "In a xenograft tumor mouse model, UA was able to prolong animal life in pancreatic cancer by inhibiting tumor development via the PI3K/AKT/mTOR pathway." (PMID 38849679, 2024). "Conversely, ectopic overexpression of Gαi3 led to an increase in the phosphorylation of Akt (Ser-473) and S6 in priPC-1 cells, highlighting Gαi3’s critical role in Akt-mTOR pathway activation in the pancreatic cancer cells." (PMID 39349432, 2024). "Previous reviews have described the roles of GSK3β in mediating Notch and mTOR signaling in different cancer types, including pancreatic cancer." (PMID 38318525, 2024). "Collectively, these findings highlight Gαi3’s critical role in promoting pancreatic cancer cell growth, potentially through the modulation of the Akt-mTOR and PKA-Hippo-YAP pathways and its influence on the immune landscape." (PMID 39349432, 2024).
pancreatic cancer (continued). "Temsirolimus is another mTOR inhibitor which showed promise in xenograft models of Pancreatic cancer, however clinical translation resulted in lesser efficacy." (PMID 38474109, 2024). "The current study substantiates these findings by demonstrating that Gαi3-mediated pancreatic cancer cell growth is mediated, at least in part, by promoting the Akt-mTOR pathway activation." (PMID 39349432, 2024). "The reported mechanisms by which PSCs and CAFs interact with and induce chemoresistance in pancreatic cancer cells involve the Notch, mTOR, and IL-6/JAK/STAT3 pathways." (PMID 38318525, 2024). "MINDY Lysine 48 Deubiquitinase 2 (MINDY2) interacts with and deubiquitinates ACTN4, stabilizes ACTN4, and activates the PI3K/AKT/mTOR signaling pathway to promote pancreatic cancer proliferation and metastasis." (PMID 39115875, 2024). "Introduction of caAkt1 to restore Akt-S6 activation compensated for the proliferation and migration inhibition of Gαi3-silencing pancreatic cancer cells, indicating a partial reliance of Gαi3-driven pancreatic cancer cell growth on Akt-mTOR pathway activation." (PMID 39349432, 2024). "It has been reported that ALDH1A3 activates the PI3K/AKT/mTOR signaling pathway by cross‐talking with the transcription factor PPARγ in pancreatic cancer." (PMID 37551838, 2023). "Here bioinformatics studies and protein chip analyses of MXRA5-overexpressed pancreatic cancer cells revealed that MXRA5-associated DEGs and differentially DEPs are both enriched in PI3K-Akt-mTOR cascade." (PMID 36828810, 2023). "Specifically, in pancreatic cancer CXCL12-CXCR7 axis promotes migration and invasion of pancreatic cancer cells, through mTOR and Rho/ROCK pathway." (PMID 37035150, 2023). "CDK4/6 inhibitors in combination with phosphatidylinositol 3‐kinase (PI3K)/mTOR or TGFβ receptor type I (TGFβ‐RI) inhibitors have confirmed efficacy in preclinical pancreatic cancer models." (PMID 37840530, 2023). "Everolimus (Evr) is an inhibitor of the mammalian target of rapamycin (mTOR) that modulates glucose metabolism, tube formation, cell migration, and apoptosis in pancreatic cancer cells by inhibiting the activation of the PI3K/AKT/mTOR signaling pathway." (PMID 36975494, 2023). "We further demonstrate that 8a sensitize pancreatic cancer cells to gemcitabine via reversing the activation of PI3K/AKT/mTOR and ERK signaling pathways induced by gemcitabine and blocking the DNA damage repair pathway." (PMID 37542062, 2023). "Bioinformatics studies and the protein chip analyses revealed that differentially expressed genes (DEGs) and differentially expressed proteins (DEPs) in MXRA5-overexpressed primary pancreatic cancer cells were enriched in the PI3K-Akt-mTOR cascade." (PMID 36828810, 2023). "Metformin also prevented pancreatic cancer progression via suppression of both mTOR and autophagic induction." (PMID 37760498, 2023). "We also found that NB decreases SOD2 expression and negatively impacts the PI3K/Akt/mTOR pathway, leading to the inhibition of growth in pancreatic cancer cells." (PMID 37891871, 2023). "Lu also found that irradiation promoted mTOR expression and activation in pancreatic cancer cells through reducing miR-99b expression." (PMID 37056929, 2023). "In this study, we discovered the effect of KV on mediating the PI3K-Akt-mTOR and Erk-RPS6K-TMEM139 signaling pathways in oxaliplatin-resistant AsPC-1 cells (AsPC-1 cells; KRAS-mutated pancreatic cancer cells)." (PMID 37174108, 2023). "The main effects of S100a9 in pancreatic cancer are the inhibition of NF-κB and the stimulation of mTOR, which inhibit autophagy." (PMID 37723445, 2023). "Here, we show that AUM302, a novel triple kinase PIM/PI3K/mTOR inhibitor, decreases proliferation of pancreatic cancer cell lines in vitro." (PMID 37943821, 2023).